SNORD97 (small nucleolar RNA, C/D box 97)
Synonyms: U97
Gene: Small nucleolar RNA gene on chromosome 11 (10,801,467 to 10,801,608, reverse strand). Ensembl gene ENSG00000238622.
Gene Ontology:
Biological process: RNA processing
Cellular component: nucleolus
Homologues: Orthologues: chimpanzee SNORD97 (99% identical), macaque SNORD97 (95% identical), rabbit SNORD97 (93% identical), pig SNORD97 (92% identical), guinea pig SNORD97 (92% identical), rat Snord97 (82% identical), mouse Gm23262 (78% identical), tropical clawed frog SNORD97 (70% identical), zebrafish SNORD97 (54% identical).
Diseases named in the same sentence as SNORD97 in open-access papers:
SNORD97 is named in the same sentence as 6 diseases in open-access papers, as found by Europe PMC text mining. Sharing a sentence is not in itself a finding about the gene and the disease. The quoted sentences say what the papers report.
cervical cancer (1 paper, 2021). A primary or metastatic malignant neoplasm involving the cervix. "In particular, tumor-related platelet activation by downregulation of RGS18 and an immune suppression by upregulation of both SNORA12 and SNORD97 may be essential mechanisms for cervical cancer development and progression." (PMID 34827689, 2021).
cervical squamous cell carcinoma (1 paper, 2021). A squamous cell carcinoma arising from the cervical epithelium. "The downregulation of SNORA12 and SNORD97 in tissues from patients with cervical squamous cell carcinoma implies that their secretion from cancer cells may help to evade host immunity against tumors through suppression of both systemic lymphopenia and lymphocyte activity in the TME." (PMID 34827689, 2021).
infection (1 paper, 2025). The state of being infected such as from the introduction of a foreign agent such as serum, vaccine, antigenic substance or organism. "In contrast to expression changes induced by Delta infection, RT-qPCR validation of Omicron BA.2-infected cells only identified significant regulation of SNORA62, while expression of SNORA46, SNORD97, and SNORD109B was not significantly altered." (PMID 40510596, 2025).
SNORD97 also shares sentences with these, for which no sentence is quoted: cancer (1 paper); lymphopenia (1); tumor (1).